FKTN (fukutin)
Diseases named in the same sentence as FKTN in open-access papers (continued):
Sharing a sentence is not in itself a finding about the gene and the disease.
hepatocellular carcinoma (2 papers, 2022 to 2024). A malignant tumor that arises from hepatocytes. "In hepatocellular carcinoma (HCC), a novel prognostic signature composed of 6 key lactate metabolism-related genes (FKTN, PDSS1, PET117, PUS1, RARS1, and RNASEH1) was developed to predict the survival and tumor microenvironment of HCC patients." (PMID 38529390, 2024). "In hepatocellular carcinoma (HCC), transcriptomic data revealed a lactate metabolism-related gene signature (LMRGS) based on the expression of six genes (FKTN, PDSS1, PET117, PS1, RARS1, and RNASEH1)." (PMID 36713558, 2022).
arthrogryposis (1 paper, 2021). A rare, non-progressive congenital disorder characterized by multiple joint contractures which are present at birth. "In the first case the COFS syndrome remained undiagnosed, while in the second case, due to prenatal findings of arthrogryposis and cataract, genetic investigation focusing on responsible genes of COFS (ERCC5, ERCC6 and FKTN genes) was carried out." (PMID 33766032, 2021).
brain malformations (1 paper, 2018). "Since Emx1-fukutin-cKO and Largemyd/myd mice demonstrated diffuse and severe brain malformations at E18.5, respectively, these two strains were used for rescue experiments." (PMID 29360985, 2018).
COFS syndrome (1 paper, 2021). Cerebrooculofacioskeletal (COFS) syndrome is a rare genetic disorder, belonging to a family of diseases of DNA repair, characterized by a severe sensorineural involvement. "Due to the prenatal findings, a COFS syndrome was suspected and further genetic investigation focusing on responsible genes were carried out: ERCC5, ERCC6 and FKTN genes (candidate genes included in the ILLUMINA Trusightone Clinical Exome Sequencing panel)." (PMID 33766032, 2021).
epilepsy (1 paper, 2023). A brain disorder characterized by episodes of abnormally increased neuronal discharge resulting in transient episodes of sensory or motor neurological dysfunction, or psychic dysfunction. "Therefore, defects in the FKTN gene lead to a congenital progressive muscular dystrophy characterized by brain malformation, dystrophic changes in skeletal muscle, severe intellectual deficit, epilepsy, and motor impairment." (PMID 37239976, 2023).
glioma (1 paper, 2021). A benign or malignant brain and spinal cord tumor that arises from glial cells (astrocytes, oligodendrocytes, ependymal cells). "Moreover, there is no precedent describing the incidence of malignant neoplasms such as gliomas in FCMD patients, and it is unclear whether fukutin overexpression is closely relevant to tumorigenesis in the brain." (PMID 34830034, 2021).
idiopathic inflammatory myositis (1 paper, 2022). "Other target conditions could include idiopathic inflammatory myositis and myopathies due to mutations in fukutin and POMT2." (PMID 35625891, 2022).
meningitis (1 paper, 2024). A disorder characterized by acute inflammation of the meninges of the brain and/or spinal cord. "The FCMD gene encodes Fukutin, and FCMD is a genetic disease that is caused by an autosomal recessive mutation in the 10-exon of the FCMD gene, leading to muscle weakness, hypotonia, mental retardation, and meningitis in infancy." (PMID 38785502, 2024).
Myalgia (1 paper, 2025). "Second, APC, ENO3, ACAD9, RNASEH1, FKTN, DYSF, and ATP2A1 are associated with Myalgia." (PMID 40831500, 2025).
neuroblastoma (1 paper, 2022). Neuroblastoma (NB) is the most common solid, extracranial childhood tumor. "We next evaluated the influence of fukutin expression status on the tau phosphorylation status, using a cultured neuroblastoma cell line SH‐SY5Y." (PMID 35026860, 2022).
Sinus bradycardia (1 paper, 2021). Bradycardia related to a mean resting sinus rate of less than 50 beats per minute. "In our population, two heterozygous missense VUSs in COL6A3 gene (c.1214T>C) and FKTN gene (c.-7C>G) were reported in a 61-year-old male with NM with sinus bradycardia, first degree AV block, and right axis deviation in ECG, as well as LVH in TTE." (PMID 33567613, 2021).
Skeletal myopathy (1 paper, 2022). "In the index patient of family #10, the compound heterozygous genotype of two VUS missense variants in fukutin (FKTN), inherited in trans from the mother and father, likely explains the clinical phenotype composed of skeletal myopathy and DCM." (PMID 35877578, 2022).
tumor (5 papers, 2012 to 2024). "Downregulation of ISPD, FKTN, B3GNT1, and GYLTL1B, all of which have been shown to correlate with nuclear grade and tumor stage, were significantly associated with increased patient mortality." (PMID 26220087, 2015). "We found that a number of the genes associated with αDG glycosylation including POMT1, ISPD, FKTN, B3GNT1, and GYLTL1B, inversely associated with both grade and stage of the tumor (i.e. decreased expression of these genes was associated with greater odds of higher grade and stage)." (PMID 26220087, 2015). "On the other hand, a series of other genes acting earlier in this pathway are overexpressed in tumor cells, namely DOLK, DPM1/2/3, POMGNT1, B3GALNT2, POMK and FKTN, hence exerting instead a pro-oncogenic role." (PMID 36494657, 2022).
cancer (4 papers, 2016 to 2021). A tumor composed of atypical neoplastic, often pleomorphic cells that invade other tissues. "Genes and AS events enrolled in the comprehensive prognostic signature included RHOT1 (ES), SH3KBP1 (AP), AGTRAP (AA), PACS2 (AP), RBPMS (AT), B3GNTL1 (AP), MOBP (AT), NPHP3 (ES), ABCC5 (RI), FKTN (ES) and FKBP8 (AA), many of which are known to play important roles in cancer biology." (PMID 32467664, 2020).
myopathy (3 papers, 2021 to 2022). A disease of the muscle in which the muscle fibers do not function properly. "The patient was a heterozygous carrier of missense VUS in collagen type VI alpha 3 chain (COL6A3) gene (c.1214T>C), a reported biomarker of DCM, and fukutin (FKTN) gene (c.-7C>G), associated with both DCM and myopathy." (PMID 33567613, 2021).
FKTN also shares sentences with these, for which no sentence is quoted: Walker-Warburg syndrome (7 papers); Intellectual disability (3); Duchenne muscular dystrophy (2); limb-girdle muscular dystrophy (2); muscle disorders (2); autosomal recessive deafness (1); Bardet-Biedl syndrome (1); cardiac disease (1); Cerebellar hypoplasia (1); cobblestone lissencephaly (1); congenital myopathies (1); developmental delay (1); genetic disease (1); Graves disease (1); heart failure (1); hepatic cancer (1); Joubert syndrome (1); Leukoencephalopathy (1); Lissencephaly (1); muscle-eye-brain disease (1); Obesity (1); Parkinson disease (1); Pendred syndrome (1); polymicrogyria (1); primary ciliary dyskinesia (1); progressive muscular dystrophy (1); prostate carcinoma (1); retinitis pigmentosa (1); Secondary dystroglycanopathies (1); stomach cancer (1).
A further 2 diseases each share a sentence with FKTN in 1 paper.